INPPL1 (inositol polyphosphate phosphatase like 1)
Description:
Phosphatidylinositol (PtdIns) phosphatase that specifically hydrolyzes the 5-phosphate of phosphatidylinositol-3,4,5-trisphosphate (PtdIns(3,4,5)P3) to produce PtdIns(3,4)P2, thereby negatively regulating the PI3K (phosphoinositide 3-kinase) pathways. Required for correct mitotic spindle orientation and therefore progression of mitosis (By similarity). Plays a central role in regulation of PI3K-dependent insulin signaling, although the precise molecular mechanisms and signaling pathways remain unclear. While overexpression reduces both insulin-stimulated MAP kinase and Akt activation, its absence does not affect insulin signaling or GLUT4 trafficking (By similarity). Confers resistance to dietary obesity (By similarity). May act by regulating AKT2, but not AKT1, phosphorylation at the plasma membrane (By similarity). Part of a signaling pathway that regulates actin cytoskeleton remodeling. Required for the maintenance and dynamic remodeling of actin structures as well as in endocytosis, having a major impact on ligand-induced EGFR internalization and degradation. Participates in regulation of cortical and submembraneous actin by hydrolyzing PtdIns(3,4,5)P3 thereby regulating membrane ruffling. Regulates cell adhesion and cell spreading. Required for HGF-mediated lamellipodium formation, cell scattering and spreading. Acts as a negative regulator of EPHA2 receptor endocytosis by inhibiting via PI3K-dependent Rac1 activation. Acts as a regulator of neuritogenesis by regulating PtdIns(3,4,5)P3 level and is required to form an initial protrusive pattern, and later, maintain proper neurite outgrowth (By similarity). Acts as a negative regulator of the FC-gamma-RIIA receptor (FCGR2A). Mediates signaling from the FC-gamma-RIIB receptor (FCGR2B), playing a central role in terminating signal transduction from activating immune/hematopoietic cell receptor systems. Involved in EGF signaling pathway. Upon stimulation by EGF, it is recruited by EGFR and dephosphorylates PtdIns(3,4,5)P3. Plays a negative role in regulating the PI3K-PKB pathway, possibly by inhibiting PKB activity. Down-regulates Fc-gamma-R-mediated phagocytosis in macrophages independently of INPP5D/SHIP1 (By similarity). In macrophages, down-regulates NF-kappa-B-dependent gene transcription by regulating macrophage colony-stimulating factor (M-CSF)-induced signaling (By similarity). Plays a role in the localization of AURKA and NEDD9/HEF1 to the basolateral membrane at interphase in polarized cysts, thereby mediates cell cycle homeostasis, cell polarization and cilia assembly (By similarity). Additionally promotion of cilia growth is also facilitated by hydrolysis of (PtdIns(3,4,5)P3) to PtdIns(3,4)P2 (By similarity). Promotes formation of apical membrane-initiation sites during the initial stages of lumen formation via Rho family-induced actin filament organization and CTNNB1 localization to cell-cell contacts (By similarity). May also hydrolyze PtdIns(1,3,4,5)P4, and could thus affect the levels of the higher inositol polyphosphates like InsP6. Involved in endochondral ossification.
Synonyms: SHIP2; OPSMD
Tractability: Small molecule: a structure with a bound ligand is known; a high-quality ligand is known. Antibody: UniProt places it where antibodies can reach, with medium confidence; its Gene Ontology location is reachable by antibodies, with medium confidence. PROTAC: ubiquitination databases record sites on it; its protein half-life has been measured; a small molecule that binds it is known.
Target class: Enzyme; Phosphatase
Gene: Protein-coding gene on chromosome 11 (72,223,524 to 72,239,184, forward strand). Ensembl gene ENSG00000165458.
Subcellular location: Cytoplasm, cytosol; Cytoplasm, cytoskeleton; Membrane; Cell projection, filopodium; Cell projection, lamellipodium; Basal cell membrane; Nucleus; Nucleus speckle; Cytoplasm, cytoskeleton, spindle pole
Subcellular location (Human Protein Atlas): Cytosol; Golgi apparatus
Pathways (Reactome):
Immune System: Interleukin receptor SHC signaling; Signaling by CSF1 (M-CSF) in myeloid cells
Metabolism: Synthesis of IP3 and IP4 in the cytosol; Synthesis of PIPs at the plasma membrane
Gene Ontology:
Molecular function: phosphatidylinositol-3,4,5-trisphosphate 5-phosphatase activity; protein binding; SH2 domain binding; inositol-polyphosphate 5-phosphatase activity; phosphatase activity
Biological process: actin filament organization; endochondral ossification; endocytosis; cell adhesion; establishment of mitotic spindle orientation; negative regulation of insulin-like growth factor receptor signaling pathway; phosphatidylinositol biosynthetic process; regulation of actin filament organization; regulation of immune response; regulation of protein localization; phosphatidylinositol dephosphorylation
Cellular component: cytosol; membrane; basal plasma membrane; nuclear speck; nucleus; spindle pole; cytoplasm; cytoskeleton; filopodium; lamellipodium; plasma membrane
Genetic constraint (gnomAD): Loss-of-function variants: 89 observed, 136.84 expected, observed/expected ratio (o/e) 0.65, 90% interval 0.55 to 0.78. The upper end of that interval is the gene's LOEUF score, 0.78, which puts it in group 3 of 6, group 1 being the genes least tolerant of losing a copy. Missense variants: 1,411 observed, 1,647.9 expected, observed/expected ratio (o/e) 0.86, 90% interval 0.82 to 0.89. Synonymous variants: 719 observed, 683.32 expected, observed/expected ratio (o/e) 1.05, 90% interval 0.99 to 1.12.
Gene-disease validity (ClinGen):
ClinGen rates the evidence that INPPL1 causes each of these diseases.
opsismodysplasia (autosomal recessive): Definitive. Opsismodysplasia is a skeletal dysplasia characterized by congenital dwarfism and facial dysmorphism.
Homologues: Orthologues: chimpanzee INPPL1 (99% identical), macaque INPPL1 (98% identical), dog INPPL1 (97% identical), guinea pig INPPL1 (96% identical), mouse Inppl1 (96% identical), rat Inppl1 (95% identical), rabbit INPPL1 (93% identical), pig INPPL1 (92% identical), tropical clawed frog inppl1 (72% identical), zebrafish inppl1a (52% identical), Drosophila melanogaster Synj (13% identical), Caenorhabditis elegans unc-26 (12% identical). Paralogues in human: INPP5D (38% identical), SYNJ2 (16% identical), SYNJ1 (16% identical), INPP5B (14% identical), OCRL (14% identical), INPP5E (11% identical), INPP5J (11% identical), FIG4 (11% identical), INPP5F (10% identical), INPP5K (8% identical), SACM1L (8% identical), SH2D1A (3% identical), and 1 more.